RHAG (Rh associated glycoprotein)
Description:
Component of the ankyrin-1 complex, a multiprotein complex involved in the stability and shape of the erythrocyte membrane. Heterotrimer with RHCE (RHAG)2(RHCE), that transports ammonium and its related derivative methylammonium, in both neutral and ionic forms, across the erythrocyte membrane. The transport of NH4(+) is electrogenic and masks the NH3 transport. Also, may act as a CO2 channel. In vitro, leaks monovalent cations. Moreover in erythrocyte, regulates RHD membrane expression and is associated with rhesus blood group antigen expression.
Synonyms: Rh50A; CD241; RH50; SLC42A1; OHS; OHST; RH2; RHNR; Rh50GP
Tractability: Small molecule: a structure with a bound ligand is known. Antibody: its Gene Ontology location is reachable by antibodies, with high confidence; UniProt predicts a signal peptide or a membrane-spanning region.
Gene: Protein-coding gene on chromosome 6 (49,605,175 to 49,636,839, reverse strand). Ensembl gene ENSG00000112077.
Subcellular location: Membrane
Subcellular location (Human Protein Atlas): Endoplasmic reticulum
Pathways (Reactome):
Transport of small molecules: Erythrocytes take up carbon dioxide and release oxygen; Erythrocytes take up oxygen and release carbon dioxide; Rhesus glycoproteins mediate ammonium transport
Disease: Defective RHAG causes regulator type Rh-null hemolytic anemia (RHN)
Gene Ontology:
Molecular function: ammonium channel activity; ankyrin binding; carbon dioxide transmembrane transporter activity; leak channel activity; methylammonium transmembrane transporter activity; protein binding
Biological process: ammonium transmembrane transport; carbon dioxide transmembrane transport; carbon dioxide transport; intracellular monoatomic ion homeostasis; methylammonium transmembrane transport; transmembrane transport; ammonium homeostasis; bicarbonate transport
Cellular component: ankyrin-1 complex; membrane; plasma membrane
Genetic constraint (gnomAD): Loss-of-function variants: 20 observed, 39.91 expected, observed/expected ratio (o/e) 0.5, 90% interval 0.35 to 0.73. The upper end of that interval is the gene's LOEUF score, 0.73, which puts it in group 2 of 6, group 1 being the genes least tolerant of losing a copy. Missense variants: 444 observed, 497.84 expected, observed/expected ratio (o/e) 0.89, 90% interval 0.82 to 0.96. Synonymous variants: 173 observed, 175.83 expected, observed/expected ratio (o/e) 0.98, 90% interval 0.87 to 1.12.
Homologues: Orthologues: chimpanzee RHAG (98% identical), macaque RHAG (89% identical), rabbit RHAG (83% identical), guinea pig RHAG (79% identical), dog RHAG (77% identical), mouse Rhag (77% identical), pig RHAG (77% identical), rat Rhag (77% identical), tropical clawed frog rhag (68% identical), zebrafish rhag (66% identical), Drosophila melanogaster Rh50 (46% identical), Caenorhabditis elegans rhr-1 (44% identical), and 1 more. Paralogues in human: RHCG (54% identical), RHBG (51% identical), RHCE (36% identical), RHD (35% identical).
Diseases named in the same sentence as RHAG in open-access papers:
RHAG is named in the same sentence as 59 diseases in open-access papers, as found by Europe PMC text mining. Sharing a sentence is not in itself a finding about the gene and the disease. The quoted sentences say what the papers report.
leukemia (6 papers, 1997 to 2023). A malignant (clonal) hematologic disorder, involving hematopoietic stem cells and characterized by the presence of primitive or atypical myeloid or lymphoid cells in the bone marrow and the blood. "Using RNA sequencing, we found that genes associated with AML subtypes, such as RYR3, RHAG, PCDH9, ANK1, ADAMTS3, and DLC1, were significantly up-regulated in the leukemia cells of two responders, but not in the 3 non-responders." (PMID 28900115, 2017).
thalassemia (2 papers, 2019 to 2025). An inherited blood disorder characterized by a decreased synthesis of one of the polypeptide chains that form hemoglobin. "Thus P11.1 with a mutation in β-spectrin as well as a mutation in RHAG and P22.1 with a mutation in α-spectrin as well as being a pyruvate kinase deficiency and a thalassemia carrier show an increase both in their inward and outward current." (PMID 31040790, 2019).
red blood cell disorders (1 paper, 2022). "Consistent with the role of red blood cell disorders, we also found associations of RHAG (Rh Associated Glycoprotein) and SPTA1 with decreased levels of HbA1c." (PMID 36088354, 2022).
RHAG also shares sentences with these, for which no sentence is quoted: tumor (40 papers); cancer (38); breast carcinoma (11); hepatocellular carcinoma (7); lung carcinoma (6); liver cancer (5); malaria (5); prostate carcinoma (5); cervical cancer (3); glioblastoma (3); infection (3); osteosarcoma (3); Arthritis (2); brain tumor (2); breast tumor (2); cognitive deficits (2); colorectal carcinoma (2); Myocardial fibrosis (2); pancreatic cancer (2); adenocarcinoma (1); asthma (1); bladder cancer (1); cardiomyopathy (1); colon carcinoma (1); cryohydrocytosis (1); depression (1); diabetes (1); diabetic nephropathy (1); emphysema (1); endometrial cancer (1).
A further 26 diseases each share a sentence with RHAG in 1 paper.